IL2 (interleukin 2)
Diseases named in the same sentence as IL2 in open-access papers (continued):
Sharing a sentence is not in itself a finding about the gene and the disease.
tumor (continued). "A preclinical study tested an in situ vaccination method combining radiotherapy, tumor-specific antibodies, and interleukin-2 (IL-2) in a mouse model." (PMID 39859231, 2025). "Since the half life of IL-2 in the circulation is short requiring more frequent administration, the intra-tumor administration is an attractive option." (PMID 40671820, 2025). "Cytokines such as IL-12 and IL-2 are promising cancer vaccine immunostimulants due to their ability to enhance tumor-specific T cell proliferation and activation, promoting cytotoxic responses and Th1 polarization." (PMID 39789208, 2025). "Interleukin-2 (IL-2) has been available in recombinant form for some time and has been given systemically or via intra-tumor injection to human cancer patients with documented efficacy." (PMID 40671820, 2025). "Depletion of FAP+ CAFs in mammary tumor models has shown a shift from IL-4 and IL-6 expression to IL-2 and IL-7 expression in tumor homogenates." (PMID 40236693, 2025). "Mdivi-1, a mitochondria fragmentation inhibitor, improved mitochondrial morphology and enhanced the tumor-killing ability of IL-2-stimulated BBζ." (PMID 40025022, 2025). "We also observed increased expression of the activation/effector markers CD25, NKG2D, CX3CR1 and CD39 on the surface of CD8+ T cells in tumor, spleen, and blood following treatment with IL-2/JES6 alone or after ICIs." (PMID 40789741, 2025). "synthesized an erythrocyte membrane‐coated nanogel to co‐deliver paclitaxel (PTX) and immune‐stimulating cytokine IL‐2 to the tumor." (PMID 41287898, 2025). "For example, delivering cytokine genes such as IL-2 enhances immune infiltration in the tumor microenvironment." (PMID 40872479, 2025). "TCR signaling cleaved Gasdermin D to form GSDMD-N pores in the plasma membrane of CD4+ T cells, which triggers Ca2+ influx to induce the expression of IL-2 to aid CD8+ T-mediated tumor cell killing." (PMID 40759573, 2025). "Although the HNSCC TME subtypes produce similar diagnoses (barring the total T cell counts in the TME) vis-à-vis different tumor cell state populations, the IL-2-based treatment in the immune desert focuses on strengthening the immune system." (PMID 40460357, 2025). "High concentrations of IL-2 and IFN-α produced locally at the RCC tumor site directly change tumor characteristics associated with the invasion and metastasis phenotype of RCC." (PMID 41181710, 2025). "In RCC, select patients have responded favorably to high-dose IL-2 therapy, with some experiencing complete tumor regression." (PMID 40677703, 2025). "Critically, the level of IL-2 induced is sufficient to expand tumor-reactive T cells while remaining below the threshold required to expand Tregs, thus preserving immune effector function." (PMID 41374974, 2025). "Pharmacokinetic and biodistribution studies confirmed liposome-anchored IL-2 showed faster clearance from the bloodstream but greater retention within the tumor." (PMID 40557148, 2025). "Tumor-specific promoters (TSPs) and logic-gated circuits (e.g., Lokon Pharma Adenovirus 703 (LOAd703) adenovirus driving IL-2 and 4-1BB Ligand (4-1BBL) via Δ24 E1A-TSP) ensuring spatially restricted transgene activation." (PMID 41425703, 2025). "The administration of high-dose IL-2 in combination with autologous lymphokine-activated killer (LAK) cells was first reported to induce tumor regression in an observational study involving 25 patients with metastatic cancer." (PMID 40647561, 2025). "Conversely, IL-2 potentiates antitumor effector functions of T cells, thereby influencing tumor cell viability and functionality." (PMID 40977688, 2025). "Tumors were cultured ex vivo for 7 days, and increased percentages of human CD45+ immune cells were seen in both untreated and IL-2-treated tumors from tumor-bearing mice with sNK infusion compared to untreated tumor-bearing mice." (PMID 40805135, 2025).
tumor (continued). "The ALI method preserves the tumor’s native immune and stromal cells, and cytokines such as IL-2 help maintain immune cell activity." (PMID 40843351, 2025). "In this study, we investigated the expression levels of IL-2, IL-10, IL-6, and TNF-α and assessed their associations with clinical and pathological tumor features." (PMID 40869161, 2025). "According to literature, triterpenoid components from FOA can increase the spleen index in tumor-bearing mice and elevate the IL-2 levels to varying degrees, suggesting that its anti-tumor effects are related to enhancing the body’s immune function." (PMID 41050420, 2025). "Concurrently, pro-inflammatory cytokines, including IFN-γ, TNF-α, and IL-2, are secreted, enhancing the anti-tumor response and facilitating the recruitment of additional immune cells into the tumor microenvironment." (PMID 40805178, 2025). "Taken together, the combination of concomitant expressions of both compounds is significantly more potent in inhibiting tumor growth than immunotherapy with IL2 alone." (PMID 41050655, 2025). "Mechanistically, the mast cells with low BTG2 suppress anti-tumor immunity by inducing Treg cell production through IL-2 secretion, particularly within tumor-draining lymph nodes." (PMID 40313959, 2025). "Sec-MesoCAR-T cells showed an enhanced inhibitory effect on BxPC-3 tumor than MesoCAR-T cells in vitro and in vivo, and secreted higher level of cytokines including IL-2, IL-6 and IFN-γ in vitro than MesoCAR-T (control) cells." (PMID 40969762, 2025). "Given UDCA’s inhibitory effect on tumor-associated TGF-β1, it is anticipated to counteract Treg cell activation induced by IL-2, thereby enhancing its antitumor efficacy." (PMID 40009662, 2025). "By 48 hours after administration, we detected an increased proportion of the IL-7–ALT dose within tumor compared to IL-2–ALT." (PMID 40244705, 2025). "In this case, IL-2 receptor β (IL2Rβ) was used to bind and inhibit IL-2 activity prior to cleavage, which converted it into its active form following matrix metalloproteinase-mediated cleavage within tumor tissues." (PMID 40557148, 2025). "Yet, restoring their expression decreased tumor cell viability and T cell exhaustion by targeting tumor PD-L1, thereby reducing IL-10 and boosting IL-2/IFN-γ." (PMID 40647470, 2025). "According to reports, a thermo-sensitive hydrogel co-loaded with DOX/IL-2/IFN-γ improved B16F10 melanoma tumor response to treatment by enhancing tumor cell death and boosting CD3+/CD4+T and CD3+/CD8+T cell proliferation." (PMID 40430316, 2025). "It inhibits T cell activation by binding with high affinity to MHC-II molecules on antigen-presenting or tumor cells, suppressing IL-2 and IFN-γ secretion." (PMID 40948781, 2025). "It has been reported that IL2-expressing Vaccinia virus strains have variable toxicities in mouse models and results in effective anti-tumor responses." (PMID 41050655, 2025). "Therapeutic strategies focus on enhancing the immune-activating properties of IL-2, IL-7, IL-12, and IL-15, while also suppressing the pro-inflammatory and tumor-promoting cytokines, such as TNF-α, IL-1β, and IL-6." (PMID 40508202, 2025). "Increased IL-2 expression shifts the immune response toward tumor attack, allowing NK cells, CD8+ T cells, and CD4+ T cells to infiltrate the tumor microenvironment, while miR-217 downregulates mtKRAS expression." (PMID 41459907, 2025). "These tumor-specific Th1 cells, armed with the ability to produce IFN-γ and IL-2, subsequently traffic back to the tumor, where they significantly enhance the activity of tumor-infiltrating cytotoxic CD8+ T cells, contributing to tumor cell lysis and control." (PMID 40432108, 2025). "In contrast, IL-2 exhibited the lowest frequency of high expression (28.7%), indicating relatively limited activity in tumour tissue." (PMID 41465261, 2025). "CD8 + T and NK cells can attract tumor cells, promoting the secretion of cytokines such as IL-2, IL-12, and IFN-γ and inflammatory responses." (PMID 40833956, 2025).
tumor (continued). "By upregulating NKG2D receptor expression and activating immune cells, IL-2 and IL-15 enhance the antitumor response in LNs, potentially improving local immune interventions and aiding in tumor control." (PMID 40636453, 2025). "A separate study demonstrated that IL-2 not only facilitates the in vitro expansion of tumor-infiltrating lymphocytes (TIL) and enhances the generation of CD8-positive TIL, thereby improving their tumor recognition and attack capabilities." (PMID 39958351, 2025). "This innovative IL-2 therapy achieves remarkable tumor suppression in both heterotopic melanoma and orthotopic GBM models, and is also applicable in preventing postsurgical tumor recurrence." (PMID 40009662, 2025). "Contrarily, human γδ thymocytes inherently lean toward differentiating into γδ T cells upon stimulation with IL-2 or IL-15, and are consequently more inclined to exhibit anti-tumor effects within the TME." (PMID 40148988, 2025). "Studies have shown that CD8+CD14+ T-cells accumulate in liver allografts and during hepatic viral and tumor-specific responses in a mouse model, producing IL-10 and IL-2 ex vivo." (PMID 41148820, 2025). "Consistent with the in vitro findings, anti-GITR–expanded TILs significantly inhibited tumor growth by 56% at day 45 compared to the control group receiving IL-2 alone." (PMID 41280919, 2025). "OKT3 better preserves a less differentiated T cell phenotype, with T cells expanded using OKT3/IL-2, showing a stronger effector memory profile, which is beneficial for tumor-killing." (PMID 40243610, 2025). "In experimental MHC-I deficient tumor models NK cell dysfunction can be reversed by cytokines including (engineered) IL-2 and combinations of IL-12 and IL-18 which promotes tumor clearance." (PMID 40849493, 2025). "One of the most studied IL-2 immunocytokines has been L19-IL-2, targeting the neoangiogenesis tumor-specific B-FN isoform." (PMID 39852848, 2025). "Flow cytometric analysis revealed more cytotoxic CD8+ T-cells with higher IFNγ, TNFα, and IL2 expression—indicative of a more effective anti-tumor immune response (SF." (PMID 40951290, 2025). "Some immunotherapies are based on immunomodulation and the addition of exogenous molecules, such as cytokines (e.g., IL-2) or antibodies targeting tumor-immune cell interactions (e.g., PD-1/PD-L1 or HER-2)." (PMID 40710292, 2025). "For example, interleukin-2 (IL-2) and adoptive transfer of autologous tumor-infiltrating lymphocytes (TILs) were found to increase the chances of long-term survival, even in patients with a poor prognosis." (PMID 40141358, 2025). "Both IL‐2 and Y45 significantly reduced tumor growth compared to PBS; however, survival benefits were limited." (PMID 40108893, 2025). "IL-2 as a monotherapy has demonstrated low to moderate anti-tumor efficacy in patients with metastatic melanoma and metastatic renal cell cancer." (PMID 40502703, 2025). "TILs isolated from tumors treated with IL-2-expressing oncolytic virus maintained high tumor specificity after ex vivo expansion." (PMID 41024300, 2025). "A preclinical study using xenograft models of head and neck squamous-cell carcinoma in immunocompromised rats indicated that intertumoral administration of liposomal IL-2 significantly enhanced drug retention and diffusion within the tumor." (PMID 40143046, 2025). "In our study, we identified a notable trend suggesting a relationship between IL-2 expression and tumor stage." (PMID 40869161, 2025). "To further improve knowledge in this area, we investigated the role of cytokines that influence T-cell biology and showed that low levels of circulating IL-2 also seemed to correlate with improved tumor response." (PMID 39927513, 2025). "PD-L2 suppresses T cell activation and proliferation by binding to the PD-1 receptor on the surface of T cells, while suppressing interleukin (IL)-2 production and promoting immune escape of tumours." (PMID 40994140, 2025).
tumor (continued). "This suggests that the CD62L+ Tcm cells resulting from YD treatment exhibit a higher differentiation proficiency into effector cells within the tumor compared to those from Y45 or IL‐2 treatment." (PMID 40108893, 2025). "Th1 CD4+ T-cells release pro-inflammatory signals, such as interferon-gamma (IFN-γ) and interleukin-2 (IL-2), which lead to the maturation of APCs and thus enhanced tumor antigen presentation to CD8+ T-cells." (PMID 40362529, 2025). "Th1 cells release anti-tumor cytokines like interleukin (IL)-2, interferon (IFN)-γ, and tumor necrosis factor (TNF)-α, while Th2 cells release immunosuppressive IL-4, IL-5, IL-10, and IL-13." (PMID 40260236, 2025). "In the realm of cellular therapy, tumor-infiltrating lymphocytes (TILs) infused after lymphodepleting preconditioning and supported by high-dose IL-2 can penetrate the BBB and eradicate micrometastases." (PMID 40666508, 2025). "Elevated levels of IL-2 and PDL-1 were significantly associated with favorable clinical responses to ICI therapy, consistent with previous studies linking robust anti-tumor immune response to cytokine-mediated T-cell activation." (PMID 40697375, 2025). "Here we show that tissue-scale spatial structure can have a profound impact on the resilience of tumours to immunotherapy using a classical model incorporating IL-2 compounds and effector cells as treatment parameters." (PMID 40591070, 2025). "Particularly, in the TME, it has been reported that the source of IL-2 switches from CD8+ T cells to CD4+ T cells during tumor progression." (PMID 40759573, 2025). "A key mechanism of action of STAT3 is to promote the proliferation and survival of tumor cells by mimicking physiological growth-promoting signals (IL-2 and T-cell receptor (TCR) signaling pathways), thereby playing a critical role in ALCL formation." (PMID 41584605, 2025). "Cytokines such as VEGF, IL‐1β, PDGF, and FGF promote tumor formation, and IFNs, IL‐2, IL‐12, and IL‐15 inhibit tumor growth." (PMID 40356340, 2025). "IL-10 can inhibit the production of IL-2 by T cells and suppress the antitumor immune response, thus making the tumor further deteriorate (Arany, Grattendick, & Tyring, 2002)." (PMID 41399789, 2025). "For instance, the IL-2 conjugated with tumor-targeting antibodies showed promise in the preclinical models of gastric carcinoma." (PMID 40309351, 2025). "Briefly, TILs were grown from the tumor fragments in high-dose IL-2 conditions and stimulated with anti-CD3/CD28 microbeads at day 0 as shown in." (PMID 40145091, 2025). "Consistently, the combination regimen substantially elevated the concentrations of TNF-α, IFN-γ, and IL-2 in peripheral blood, spleen, and tumor tissue." (PMID 41408296, 2025). "CD8+ T cells expressing IFN-γ or IL-2 from the tumor-draining lymph node (TDLN) were found to be activated in the UMSC/miR-124-PD-1 and its exosomes treated group." (PMID 40134003, 2025). "These immunocytokines have effects on tumor growth that are comparable to those of untargeted IL-2 when administered intravenously." (PMID 41562774, 2025). "Especially in tumor immunotherapy, where the use of IL-2 sometimes significantly increases the therapeutic effect, IL-2 promotes the proliferation and activation of effector T cells and enhances anti-tumor, antiviral and antibacterial immune responses." (PMID 41376630, 2025). "Among them, preconditioning NK cells with interleukin-2 (IL-2) and interleukin-15 (IL-15) has shown promise in enhancing both their expansion and cytolytic performance against tumor cells." (PMID 41567203, 2025). "In pancreatic ductal adenocarcinoma (PDAC), increased levels of IL-2 correlate with improved patient survival and enhance anti-tumor immunity, particularly by increasing CD8+ T cells, B cells, and NK cells." (PMID 39958351, 2025). "The secretion of interferon-γ (IFN-γ) interleukin-2 (IL-2) also stimulated T helper cell-1, contributing anti-tumor immune effects." (PMID 40563603, 2025).
tumor (continued). "This strategy was taken one step further by anchoring IL-2 along with the immunostimulatory agonist anti-CD137 on the surface of stealth liposomes modified with polyethylene glycol (PEG) to improve tumor accumulation by active targeting." (PMID 40557148, 2025). "Therapeutic cytokines like interleukin-2 (IL-2) and interleukin-12 (IL-12) can drive T cell proliferation and activate anti-tumor immune responses." (PMID 40963596, 2025). "We noted that TUBA1B overexpression is linked to key immune-related pathways in the tumor immune microenvironment (TIME), such as IL-6/JAK/STAT3 signaling, IL-2/STAT5 signaling, TGF-Beta signaling, and interferon responses." (PMID 39968182, 2025). "CIK cells refer to NK cells that are grown outside of the body and are stimulated with cytokines like interleukin-2 (IL-2) to enhance their anti-tumour activity and cytokine production." (PMID 40075668, 2025). "Another important T cell population is CD4+ T cells, which help create an anti-tumor microenvironment by secreting inflammatory cytokines like IL-2." (PMID 39888529, 2025). "Utilizing bilateral flank tumor model, it has been reported that the intratumoral injection of the membrane-tethered IL-2-armed oncolytic virus (vvDD-mIL2) plus CpG oligodeoxynucleotide can trigger systemic immunization." (PMID 39852848, 2025). "Prostaglandin E2, an unsaturated fatty acid secreted by tumor cells, suppresses T cell responses both indirectly by modulating inflammatory monocytes and directly by reducing T cell sensitivity to IL-2, thereby impairing their anti-tumor activity." (PMID 40658684, 2025). "Upon injection of IL2-loaded Ni-ALGMs into the tumor, IL2 is gradually released over an extended period." (PMID 40104647, 2025). "Mice completely cured by IL-2/JES6 alone or ICIs plus IL-2/JES6 were highly resistant to CT26 tumor rechallenge, demonstrating that treatment led to robust, durable antitumor immunity." (PMID 40789741, 2025). "Immunocytokines, which are antibody-cytokine fusion proteins that enhance tumor-specific delivery of immunostimulatory factors such as IL-2, TNF-α, or IL-12, show significant therapeutic potential." (PMID 40177538, 2025). "By selectively binding to PD-1 on TILs, AWT020 delivers a dual benefit: it blocks the inhibitory PD-1 pathway and provides IL-2 signaling to promote the expansion of tumor-antigen-specific T cells." (PMID 40046051, 2025). "Despite reduced expression of canonical cytotoxic markers CD16 and CD56, TGF-β expanded γδ T cells displayed superior anti-tumor efficacy compared to standard IL2/ZOL expanded γδ T cells in an OS lung metastasis model when combined with ZOL and IFO." (PMID 40969756, 2025). "PEG-polyglutamate micelles encapsulating IL-2 showed prolonged circulation and enhanced dendritic cell (DC) vaccine efficacy in tumor-bearing mice, leading to strong CTL responses." (PMID 41181109, 2025). "Concurrently, MSCs were engineered with a hypoxia-inducible promoter and NAD(P)H: quinone oxidoreductase 1 (NQO1), responsible for regulating the production of IL-2 within the tumor microenvironment." (PMID 39971901, 2025). "For instance, the A3 CBD domain of von Willebrand factor (VWF) was fused with IL-2 to facilitate targeted cytokine delivery to tumors, capitalizing on the leaky vasculature typical of tumor tissues." (PMID 40557148, 2025). "In line with this, jun-overexpressing CAR T cells exhibited enhanced tumour lysis and increased IL-2 and IFN-γ production subsequent to in vitro co-culture with leukemia cells." (PMID 39859271, 2025). "Although this model does not represent a patient-derived xenograft, anti-GITR–expanded TILs significantly inhibited tumor growth by 56% at day 53 compared to the vehicle (IL-2) control group." (PMID 41280919, 2025). "Recent studies have highlighted the potential of combining the pro-immune mechanisms of IL-2 and anti-PD-1 therapy for improved anti-tumor outcomes." (PMID 40699676, 2025).